AXL (AXL receptor tyrosine kinase)
Diseases named in the same sentence as AXL in open-access papers (continued):
Sharing a sentence is not in itself a finding about the gene and the disease.
malignant glioma (1 paper, 2012). A grade III or grade IV glioma arising from the central nervous system. "To determine whether the antiinvasive effect of EZH2 knockdown in malignant glioma cells is mediated by AXL we used siRNA to inhibit AXL expression." (PMID 23077658, 2012).
medullary thyroid carcinoma (1 paper, 2022). "AXL has also been verified to be highly expressed in anaplastic and medullary thyroid carcinoma, and research referring to AXL-targeted inhibitors in anaplastic or medullary thyroid carcinoma has yielded clinical value." (PMID 36203174, 2022).
metastasis (1 paper, 2021). The spread or migration of cancer cells from one part of the body (where they first appeared) to another. "More importantly, AXL expression was further associated with lymph node and lung metastasis." (PMID 33850249, 2021).
metastatic colorectal cancer (1 paper, 2023). "AXL is a predictor of poor survival and of resistance to anti‐EGFR therapy in RAS wild‐type metastatic colorectal cancer." (PMID 36409270, 2023).
mucinous ovarian cancer (1 paper, 2024). An invasive malignant neoplasm that arises from the ovary and is characterized by the presence of malignant epithelial cells that contain intracytoplasmic mucin and may resemble the epithelial cells of the endocervix or gastrointestinal tract. "Although miR-515-3p regulates oxaliplatin sensitivity in mucinous ovarian cancer, in part by targeting AXL, there is still a lack of sufficient evidence demonstrating the roles of miRNAs in regulating the GAS6/AXL pathway." (PMID 38539161, 2024).
multiple sclerosis (1 paper, 2025). A progressive autoimmune disorder affecting the central nervous system resulting in demyelination. "We have targeted the AXL gene for the prevention of Multiple Sclerosis using ASOs (antisense oligonucleotides), which provides a rapid and high-throughput method for silencing AXL gene expression." (PMID 39974615, 2025). "This is the first approach for the treatment of Multiple Sclerosis using Antisense Oligonucleotide therapeutics targeting AXL gene." (PMID 39974615, 2025).
myeloid leukemia (1 paper, 2017). A clonal proliferation of myeloid cells and their precursors in the bone marrow, peripheral blood, and spleen. "Thus, in keeping with the cloning of AXL as a transforming gene overexpressed in myeloid leukemia high expression levels of AXL may facilitate its ligand-independent activation." (PMID 28118606, 2017).
myopia (1 paper, 2020). "Our study found AXL and RCC associated with height and weight across the life course analyses but a decrease in MSE (increase in myopia) was only found to be associated with an increase in height at age 15 years." (PMID 32641126, 2020).
nephrolithiasis (1 paper, 2024). The presence of a calculus in the pelvis of the kidney; this is most often composed of mineral salts and proteins. "Differential expression of AXL, HIP1R, JUP, CTNNB1, and DSG2 was confirmed via PRM, suggesting their potential roles in the development and advancement of nephrolithiasis, warranting further exploration." (PMID 39114033, 2024).
ovarian endometriosis (1 paper, 2008). A non-neoplastic disorder characterized by the growth of endometrial tissue in the ovaries. "Overexpression of both AXL and GAS6 in ovarian endometriosis has previously been demonstrated using RT-PCR analysis and IHC." (PMID 19055724, 2008).
Pan (1 paper, 2024). "Overexpression of AXL, or its ligand GAS6, is frequently associated with the mesenchymal subtype and poor prognosis in GBM, and both AXL and GAS6 are listed as cancer driver genes in a recent Pan-Cancer CPTAC study." (PMID 39087397, 2024).
pleomorphic liposarcoma (1 paper, 2015). Pleomorphic liposarcoma (PLS), the rarest subtype of liposarcoma (LS), is an aggressive, fast growing tumor located usually in the deep soft tissues of the lower and upper extremities. "However, the role of AXL in the pathogenesis of well-differentiated (WDLPS), dedifferentiated (DDLPS), and pleomorphic liposarcoma (PLS) has not yet been determined." (PMID 26573603, 2015).
rectal cancer (1 paper, 2026). A primary or metastatic malignant neoplasm that affects the rectum. "AXL serum levels in the rectal cancer cohort were significantly different from healthy subjects but did not correlate with tumor stage or survival during and after neoadjuvant/adjuvant therapy." (PMID 41563267, 2026). "For AXL, significantly lower serum levels were found in the rectal cancer patients (p<0.0001, two-sided unpaired t-test, mean: 34.5 vs. 20.2 ng/mL in the controls." (PMID 41563267, 2026). "Overall, our findings suggest that AXL expression in the serum may serve as a biomarker for rectal cancer presence, while C-MET shows potential utility as a marker for therapy response and radiation-induced tissue changes." (PMID 41563267, 2026). "Serum levels of AXL were significantly lower in rectal cancer patients." (PMID 41563267, 2026). "Serum levels of soluble surface markers AXL and C-MET were retrospectively analyzed in 164 rectal cancer patients with additional immunofluorescent analyses of their primary tumor tissues." (PMID 41563267, 2026). "This study focused on the expression and diagnostic/prognostic potential of the two tyrosine kinases, AXL and C-MET, in rectal cancer, individually or in combination." (PMID 41563267, 2026). "The significance of the serum levels of AXL and C-MET was assessed in all rectal cancer patients and compared with the group of healthy individuals (n=39)." (PMID 41563267, 2026). "Serum levels of soluble surface markers AXL and C-MET, described for cancer stem cells in rectal cancer, possibly can correlate with clinicopathological characteristics and patient outcome data with respect to neoadjuvant chemoradiotherapy." (PMID 41563267, 2026). "In this study, we analyzed serum expression levels of the two potential biomarkers, AXL and C-MET, in a cohort of 164 patients with newly diagnosed rectal carcinoma." (PMID 41563267, 2026). "There had been particularly no studies regarding the expression of AXL as a suitable blood biomarker in rectal cancer patients throughout neoadjuvant treatment protocols, which was investigated for the first time in this study." (PMID 41563267, 2026). "AXL and C-MET serum levels in rectal cancer are significantly different from healthy subjects but did not correlate with tumor stage or survival during and after neoadjuvant/adjuvant therapy, while C-MET may hold promise for influencing future treatment responses." (PMID 41563267, 2026).
sarcoidosis (1 paper, 2022). Sarcoidosis is a multisystemic disorder of unknown cause characterized by the formation of immune granulomas in involved organs. "Our results also identified other fibrogenesis-associated genes as DEGs in sarcoidosis lungs including AXL, involved in migration, aggregation, and anti-inflammation through inhibition of Toll-like receptors (TLRs)." (PMID 36388923, 2022).
serous ovarian tumor (1 paper, 2020). "We also demonstrated a positive correlation between p85β and AXL levels in an independent serous ovarian tumor set (n = 49) by immunohistochemistry (Pearson’s correlation coefficient r = 0.6, P < 0.0001)." (PMID 32385243, 2020).
soft tissue neoplasm (1 paper, 2022). A benign, intermediate, or malignant neoplasm that arises from the soft tissue. "Other RTKs, such as FGFR1 and AXL in the soft tissue tumors, and FGFR1 and ALK in MB-WNT, showed absolute values in the 90th percentile of all tumors, revealing potential therapeutic susceptibilities." (PMID 35978432, 2022).
Stroke (1 paper, 2026). Sudden impairment of blood flow to a part of the brain due to occlusion or rupture of an artery to the brain. "Although AXL has been implicated in debris clearance and inflammatory regulation, its role in post-stroke myelin repair remains unclear." (PMID 41524160, 2026).
T cell lymphomas (1 paper, 2019). "The authors suggest a possible tumor suppressor role for AXL in T cell lymphoma by upregulation of LIGHT." (PMID 31694201, 2019). "However, we still need to consider that AXL is rather low or absent in T cell lymphomas and has been overexpressed in this specific cell type." (PMID 31694201, 2019).
thrombosis (1 paper, 2025). "Although thrombosis outcomes were not assessed in the patients of this study, the increased AXL expression and activation may similarly contribute to the formation of platelet‐derived thrombosis." (PMID 40476695, 2025).
type 2 diabetes (1 paper, 2025). "The aim of the current work was to investigate the potential role of GAS6, AXL, GAS6-AS1, and GAS6-DT in type 2 diabetes development and progression to DN, as well as their potential utility as biomarkers for DN in Egyptian patients." (PMID 41233312, 2025).
uterine serous carcinoma (1 paper, 2016). "In a xenograft model of human uterine serous carcinoma with AXL-deficient ARK1 cells, there was significantly less tumor burden than xenografts with control ARK1 cells." (PMID 27764792, 2016).
Wilms tumor (1 paper, 2020). An embryonal neoplasm characterized by the presence of epithelial, mesenchymal, and blastema components. "All Wilms tumor cell lines have a major activation of three tyrosine kinase receptors: EGFR, PDGFR and AXL, detected by their strong phosphorylation." (PMID 33379206, 2020).
tumor (589 papers, 2007 to 2026). "AXL, a receptor tyrosine kinase implicated in tumor progression, undergoes post-translational modifications that regulate its activity and stability." (PMID 42055283, 2026). "The mechanism by which cabozantinib exerts anti-tumor effects in PNs is not fully understood, but is postulated to be associated with downregulation of AXL, fibroblast regulation, and collagen production within the tumor microenvironment." (PMID 40732327, 2025). "Dysregulated AXL expression has been linked to increased tumor progression and metastasis and impaired tumor immunogenicity." (PMID 41009462, 2025). "The Gas6/AXL signaling pathway is closely related to the malignant behavior of tumor cells and can cause immunosuppression." (PMID 40538442, 2025). "It has been demonstrated that the ATP-competitive inhibitors of AXL inhibit tumor growth in animal models by causing BC cells to undergo apoptosis." (PMID 39755633, 2025). "AXL expression in AML is linked to pathobiology, and aberrant activation of AXL in tumor cells promotes proliferation, survival and therapy resistance." (PMID 40122885, 2025). "A strong correlation exists between AXL and PD-L1 expression, with high levels of AXL in tumor cells associated with lower response rates and shorter progression-free survival following anti-PD-1 treatment." (PMID 39924521, 2025). "Studies have shown that activation of AXL promotes tumour-associated macrophage polarisation to Type M2, which in turn contributes to tumour growth, enabling tumours to evade the immune system attack." (PMID 40088262, 2025). "c-MET and AXL are associated with tumor progression and a poor prognosis, and previous studies have shown that the activation and increased expression of AXL are critical for the development of resistance to midostaurin and quizartinib." (PMID 38978049, 2024). "AXL activation can lead to the generation of persister cells, a subpopulation of cancer cells that can survive treatments and potentially cause tumor recurrence." (PMID 39273190, 2024). "AXL expression was closely associated with tumor PD-L1 expression, particularly in tumors with VHL gene inactivation." (PMID 39014460, 2024). "Spatial-immunophenotyping provided evidence that tumor-cell AXL-upregulation and adverse mutations modulate the tumor microenvironment in favor of infiltrating, activated neutrophils over anti-tumor immune-subsets including CD4 and CD8 T-cells." (PMID 39238637, 2024). "A study in DMG found that the RTK, AXL, is upregulated in DMG, initiates the mesenchymal transition, and dual AXL/HDAC inhibition caused a synergistic anti-tumor effect." (PMID 38183103, 2024). "We sought to interrogate AXL expression in conjunction with mutational and tumor-microenvironmental features to uncover predictive mechanisms of resistance in ICI-treated NSCLC patients." (PMID 39238637, 2024). "This phenomenon showed that the mesenchymal-like cells support the crosstalk with tumor-associated macrophages (TAMs), and targeting AXL inhibits the invasion of TNBC by suppressing the EMT process and TAMs." (PMID 37538794, 2023). "The receptor tyrosine kinase AXL has been shown to be highly expressed in several major types of cancers and is closely associated with tumor progression." (PMID 37328828, 2023). "The receptor tyrosine kinase AXL is a member of the receptor family (tumour-associated macrophages) TAM and has been identified as a therapeutic target due to its role in tumour invasion and migration." (PMID 36982551, 2023). "AXL signaling is implicated in tumor growth, EMT, angiogenesis, metastasis spread, and the development of resistance to targeted therapy." (PMID 37842234, 2023). "Chiu and colleagues found that in oral squamous cell carcinoma, AXL signaling controls the polarization of tumor-associated macrophages toward the M2 phenotype with elevated expression of M2 markers and genes." (PMID 37265798, 2023).
tumor (continued). "The selective overexpression of AXL in GI malignancies is associated with a poor clinical prognosis, proliferation, metastasis, immunosuppressive tumor microenvironment, and drug resistance." (PMID 37469409, 2023). "Among them, three (NAMPT, PCDHA4, and AXL) have been reported to be associated with the pathogenesis of this tumor." (PMID 36918772, 2023). "As previously reported, PLAU and its receptor PLAUR were involved in regulating cell adhesion and promoting tumor cell migration, while c-Myc and AXL were associated with EMT, invasiveness, and migration." (PMID 35680853, 2022). "In this report, antigen uptake of cDC1s was specifically dependent on the phagocytic cell-surface receptor AXL in association with the load of apoptotic cells within tumor microenvironment." (PMID 35832091, 2022). "AXL-CAR T cells alone cause moderate tumour regression in subcutaneous and pulmonary metastatic lung cancer cell-derived xenograft models." (PMID 36261437, 2022). "AXL targeting is frequently associated with better response to anti-PD-1 in various syngeneic mouse tumor models." (PMID 35572601, 2022). "Since AXL is implicated in tumor angiogenesis, its role in acquired resistance to angiogenesis inhibitor therapy has been of great interest." (PMID 35158733, 2022). "Other convincing studies exploiting distinct immunocompetent mouse tumor models have provided further evidence for a causal role of AXL in mounting an immunosuppressive TIME." (PMID 35572601, 2022). "AXL receptor tyrosine kinase and its ligand growth arrest-specific 6 (Gas6) have been implicated in tumor growth and proliferation of NSCLC." (PMID 36547898, 2022). "Treatment efficacy was assessed by tumor volume evaluation, survival analysis, and histological evaluation of tumors, and associated with AXL expression." (PMID 35886842, 2022). "In recent years, AXL has been implicated in a variety of biological processes leading to tumor progression, metastasis, and resistance to therapies." (PMID 35158733, 2022). "AXL is a receptor tyrosine kinase, which belongs to the tumor-associated macrophage family (TAM), including TYRO-3 and MER." (PMID 35454838, 2022). "AXL is a receptor tyrosine kinase associated with tumor cell proliferation, metastasis, EMT, and drug resistance." (PMID 35999456, 2022). "Gas6/AXL signaling pathway is associated with tumor growth, metastasis, invasion, angiogenesis, drug resistance, and immune regulation, making AXL a potential target for several cancer therapies, including NSCLC." (PMID 33740988, 2021). "All of these results indicated that the AXL expression was significantly associated with immune infiltration, tumor microenvironment, methyltransferase in ccRCC." (PMID 34838035, 2021). "In terms of immunity, AXL was dramatically linked to tumor microenvironment, immune cells, immune infiltration, immune checkpoint molecules and tumor mutational burden (TMB)." (PMID 34838035, 2021). "In cancer the Gas6/AXL signaling pathway is associated with tumor cell growth, metastasis, invasion, epithelial–mesenchymal transition (EMT), angiogenesis, drug resistance, immune regulation, and stem cell maintenance." (PMID 34745951, 2021). "Increased AXL expression was associated with increased tumor cell invasiveness and tumor grade and predicted poorer survival in patients with NSCLC." (PMID 34830794, 2021). "During the process of efferocytosis, MERTK and AXL have been implicated as promoters of tumor cell survival in many hematopoietic malignancies, including acute leukemia, chronic leukemia, and multiple myeloma." (PMID 32346605, 2020). "The suppression of immune response and the remodeling of the TME, especially by polarizing macrophages in the M2 subtype (pro-tumor subtype), are other mechanisms associated to AXL and tightly interconnected with drug resistance." (PMID 33182542, 2020).